CD36 (CD36 molecule (CD36 blood group))
Diseases named in the same sentence as CD36 in open-access papers (continued):
Sharing a sentence is not in itself a finding about the gene and the disease.
atherosclerosis (continued). "The potential of CD36 as a therapeutic target for atherosclerosis and other complications of metabolic syndrome is therefore emphasized by our increasing knowledge of its mode of action and certainly warrants the development of novel alternatives aimed to correct for these metabolic defects." (PMID 29883404, 2018). "After CD36 recognizes ox-LDL in association with Toll-like receptor (TLR)s, nuclear factor (NF)-κB is activated and the inflammatory cascade is triggered, deteriorating the initiation and progression of atherosclerosis." (PMID 29896109, 2018). "In addition, we have previously demonstrated that patients with familial hypercholesterolemia and thereby increased risk of atherosclerosis, had higher levels of both CD14+ MVs and CD14+CD36+ MVs compared to healthy controls." (PMID 30425991, 2018). "ABCA1, ABCG1, ACAT1, and CD36 are positive or negative regulators of atherosclerosis." (PMID 30105261, 2018). "Deletion of PXR attenuates the development of atherosclerosis in PXR and apoE double knockout (PXR-/- and ApoE-/-) mice, which may be associated with the reduction of CD36 expression and lipid uptake in macrophages." (PMID 30319417, 2018). "Therefore, we propose that CD146 promotes atherosclerosis by CD36-dependent production of retention factors including netrin-1." (PMID 28084332, 2017). "This distinguishes CD36 from other scavenger receptors, e.g., those of class A. Additionally, S100A12 and CD36 are expressed in similar cell types, and more interestingly, the dysregulation of S100A12 and CD36 is related to similar pathological outcomes like atherosclerosis." (PMID 27734162, 2017). "CD36 is expressed on various types of cells involved in processes leading to atherosclerosis." (PMID 26925191, 2016). "Although the underlying mechanisms are not entirely understood, proatherogenic modifications of lipoproteins such as oxidized LDL-cholesterol (oxLDL-C) have been attributed to important roles in both TX development and scavenger receptor CD36-mediated atherosclerosis." (PMID 26925191, 2016). "This is consistent with a most recent study demonstrating that CD36, one of the target genes of Nrf2 determines the effects of Nrf2 on atherosclerosis through unknown mechanism." (PMID 26859892, 2016). "CD36 has anti-angiogenic nature and downregulates VEGFR2 phosphorylation, and through its ligands such as oxLDL (a major factor in the development of atherosclerosis) causes endothelial cell stiffness and atherosclerosis." (PMID 27446928, 2016). "The participation of CD36 in the control of the parasitophorous vacuole, which is an altered phagosome, has further implications for diseases such as Alzheimer’s disease, atherosclerosis, and certain bacterial infections where CD36 is a known phagocytic receptor." (PMID 27280707, 2016). "Therefore, it is important to determine the expression of CD36 when analyzing new drugs for the treatment of atherosclerosis." (PMID 25961956, 2015). "However, our previous study has shown that oxLDL did not affect the expression of scavenger receptor A and LOX1 in these cell lines and nicotine promoted foam cells and atherosclerosis via upregulation and stimulation of macrophage CD36 signaling." (PMID 26576421, 2015). "Nor did the loci correspond to any known genes involved in cholesterol transport, such as scavenger receptor A1 or CD36, which have been shown to affect atherosclerosis in some loss of function studies but not others." (PMID 26694027, 2015). "In another investigation by Zhong Q and colleagues, high density lipoprotein increased oxidized low density lipoprotein (LDL) uptake of inflammatory adipocytes via upregulation of PPARγ/CD36 pathway, which may be a new mechanism of anti-atherosclerosis." (PMID 26036798, 2015). "Likewise, the genes enriched in bacterial cell surface binding pathway have relevance to the CRP level (CRP), atherosclerosis (CD36) and inflammation (PCSK6)." (PMID 24763700, 2014).
atherosclerosis (continued). "From the clinical standpoint, the interaction between these factors might reflect the importance of CD36 in the development of atherosclerosis in RA." (PMID 25006585, 2014). "The Nrf2-mediated exacerbation of atherosclerosis may be attributable to the upregulation of CD36 expression by Nrf2." (PMID 23819012, 2013). "Monocyte/macrophage CD36 is elevated in diabetes, possibly induced by insulin resistance, and it has been proposed that this could partly explain the accelerated atherosclerosis in T2DM." (PMID 24069322, 2013). "Although the role of PAF/CD36 complex formation in atherosclerotic plaques remains to be determined, this study increases our understanding of macrophage interactions with oxLDL and provides new insights into atherosclerosis research." (PMID 24130805, 2013). "Several studies had showed that high levels of CD36 present in pre-diabetes, overt diabetes, polycystic ovary syndrome (PCOS), and impaired glucose tolerance strongly suggest that CD36 is involved in diabetes and atherosclerosis pathogenesis and acts as inflammation biomarker." (PMID 24282409, 2013). "Moreover, it has been widely studied that CD36 plays a pivotal role in the metabolic dysregulation including obesity, insulin resistance and atherosclerosis." (PMID 24016701, 2013). "In terms of atherosclerosis, there is controversy as to whether there are reduced lesions in apoE/Cd36/Msr1 triple knock-out mice, but there is consensus that absence of these receptors reduced lesion complexity and inflammation." (PMID 22470565, 2012). "In support with that hypothesis, we show that small molecules with anti-CD36 activity can reduce postprandial hyperlipidaemia and protect against type II diabetes and atherosclerosis." (PMID 22662181, 2012). "This is in agreement with the fact that CD36 depleted mice are protected against atherosclerosis." (PMID 22662181, 2012). "Such a conclusion was however challenged by the observation that combined deficiencies in scavenger A and CD36 functions did not ameliorate atherosclerosis in hyperlipidemic mice." (PMID 22662181, 2012). "Yet the role of CD36 as a target to combat atherosclerosis was criticized." (PMID 22662181, 2012). "Reviews of the role of macrophage human CD36 in atherosclerosis have been published." (PMID 24970143, 2012). "CD36 is the primary mediator of cholesterol accumulation in atherosclerosis induced by HIV PIs." (PMID 20949026, 2010). "Furthermore, the most compelling data supporting the role for CD36 in foam cell formation and atherosclerosis are from studies with CD36-knockout mice." (PMID 19604372, 2009). "Based on its role in the pathogenesis of atherosclerosis, it was hypothesized that the expression of CD36 mRNA in aortic tissues of mice fed with high fat diet will be more than mice fed with regular diet." (PMID 19604372, 2009). "Considering the profound effect of Nrf2-dependent transcriptional induction of CD36 in macrophages and the resulting impact on atherosclerosis, it is important to consider the potential pro-atherosclerotic effects of Nrf2 when designing Nrf2-targeted therapies." (PMID 19023427, 2008). "CD36 is a membrane glycoprotein involved in a variety of cellular processes such as lipid transport, immune regulation, hemostasis, adhesion, angiogenesis and atherosclerosis." (PMID 16515687, 2006). "Cluster of differentiation 36 (CD36), a crucial receptor for long-chain fatty acid uptake and lipid metabolism, has emerged as a therapeutic target for a range of lipid metabolism-related disorders, such as non-alcoholic fatty liver disease, atherosclerosis, and diabetic nephropathy." (PMID 40331957, 2025). "Moreover, Apoe/Cd36 double-null mice were resistant to diet-induced atherosclerosis." (PMID 39156133, 2024).
atherosclerosis (continued). "CD36 serves as a candidate gene for impaired fatty acid metabolism, glucose intolerance, arterial hypertension, atherosclerosis, and numerous cardiovascular diseases as well as Alzheimer’s disease and malaria, and may be imperative in the pathogenesis of human IR syndromes." (PMID 36984867, 2023). "However, there is considerable evidence showing unfavorable effects of PPARγ on foam cell formation and atherosclerosis via the transcriptional activation of CD36 and its positive correlation with ectopic lipid accumulation, including that observed in atherosclerosis." (PMID 37432260, 2023). "The ability to purify full-length SR-B1 and CD36, as well as verify their functionality, creates new opportunities to understand receptor dynamics and provides a necessary step toward understanding the molecular mechanisms behind lipid transport and atherosclerosis development." (PMID 37625590, 2023). "Therefore, targeting the CD36-mediated transport of lipid moieties could be an effective therapeutic approach for the treatment of atherosclerosis and thrombosis." (PMID 36769293, 2023). "TMAO contributes to the degenerative phase of atherosclerosis development by promoting macrophage movement and further augments atherosclerotic lesions by increasing the expression of macrophage scavenger receptors CD-36 and the SR-A1, inducing foam cell formation and impairment of in vivo RCT." (PMID 37337893, 2023). "Increased SelK gene expression promotes the subcellular transport of fatty acid transferase (CD36) because CD36 mediates the uptake of long-chain fatty acids in myocardial tissue, so SelK overexpression exacerbates lipid accumulation in cells and promotes foam cell formation and atherosclerosis." (PMID 37103050, 2023). "USP10 can interact with CD36 by removing the polyubiquitin on CD36 to stabilize the CD36 protein, thereby promoting foam cell formation and lipid accumulation and promoting the development of atherosclerosis, whereas inhibition or knockdown of USP10 can have the opposite effect." (PMID 36611964, 2022). "Moreover, NOXs increased ROS levels, helping internalize oxLDL into macrophages through CD36 and generating foam cells, which may be a universal mechanism underlying NOX‐mediated progression of atherosclerosis judging from available reports." (PMID 35386842, 2022). "Therefore, our studies raise the possibility that interfering with CD36 post-translational modification might be a potential strategy for dealing with lipoprotein disorders and atherosclerosis." (PMID 35500650, 2022). "In addition, CD36 transduces signals to mediate its role in inflammation and lipid metabolism, thus accelerating the progression of metabolic diseases including obesity, atherosclerosis, NAFLD, and type 2 diabetes." (PMID 35592528, 2022). "Therefore, CD36 participates in a wide range of cellular processes, such as apoptosis, angiogenesis, and phagocytosis in addition to fatty acid uptake, and involves in diverse diseases, such as diabetes, atherosclerosis and hypertension." (PMID 36583008, 2022). "Therefore, CD36 is often used as a biomarker of atherosclerosis in modern diagnosis and treatment." (PMID 35399657, 2022). "Hence, inhibition of CD36 is a potentially promising therapeutic strategy in atherosclerosis." (PMID 33440673, 2021). "This experimental phenomenon not only confirms the theory that ox-LDL can promote the upregulation of CD36 expression on macrophage surface, but also demonstrates that the NMs in this study have a better targeting effect on the lesion of acute advanced atherosclerosis." (PMID 34320994, 2021).
atherosclerosis (continued). "Importantly, a previous study identified an association between CD36 gene single nucleotide polymorphisms (SNPs) and decreased atherosclerosis, however, no data are available regarding the effects of these SNPs on lymphangiogenesis or lymphatic function." (PMID 33672291, 2021). "We hypothesize that CD36 is a major EC receptor for pro-inflammatory atherogenic ligands, and as such will regulate EC inflammation and have a significant impact on the initiation of atherosclerosis lesions." (PMID 34888367, 2021). "Moreover, it was reported that loss of receptor-mediated lipid uptake via SR-AI/II or CD36 pathways did not ameliorate atherosclerosis." (PMID 34944648, 2021). "CD36 is speculated to be attractive target of atherosclerosis (AS)-related thrombosis." (PMID 32059638, 2020). "CD36 may be the target of atherosclerosis (AS)-related thrombosis." (PMID 32059638, 2020). "Notably, CD36 expressed in macrophages plays a critical role in atherosclerosis." (PMID 31410189, 2019). "However, in subsequent studies, deletion of both SR-A1 and CD36 in apoE-deficient mice did not reduce atherosclerosis, suggesting the existence of alternative mechanisms of lipid uptake." (PMID 31717832, 2019). "Given the ubiquitous expression of CD36 across different cells and tissues and its pivotal role in glucose homeostasis and lipid metabolism, this signaling molecule links insulin resistance, obesity and T2D to dyslipidemia, atherosclerosis, and arterial thrombosis." (PMID 31748580, 2019). "Thus, enumerating the level of MMVs expressing CD36 may have the potential of detecting ongoing atherosclerosis." (PMID 30425991, 2018). "A more recent study in mice indicated that CLA could inhibit platelet deposition, decrease macrophage accumulation and expression of the macrophage scavenger receptor CD36 in the aorta, and increase apoptosis in atherosclerotic lesions, and thus exert a pre-resolving effect on atherosclerosis." (PMID 30347833, 2018). "Indeed, CD36 expression could be nutritionally modulated such that it could represent a valuable tool for the prevention of atherosclerosis." (PMID 26493158, 2016). "Indeed, the role of CD36 in atherosclerosis is complicated and should be further studied in detail." (PMID 26493158, 2016). "Similarly, in hyperlipidemic ApoE‐deficient mice, deletion of either CD36 or SR‐A1 significantly reduces lipid accumulation in macrophages, but does not diminish atherosclerosis." (PMID 26493158, 2016). "Therefore, if treatment increases lipolysis but reduces the CD36-mediating export of lipid, it might aggravate atherosclerosis." (PMID 25961956, 2015). "However, the role of CD36 has recently been questioned because it might make atherosclerosis worse if treatment improve the lipolysis but reduces the CD36-mediating export of lipid." (PMID 25961956, 2015). "In addition to its potential implication in atherosclerosis and dyslipidaemia, independent studies have suggested that CD36 may also be directly or indirectly involved in diabetes." (PMID 22662181, 2012). "Because CD36 is expressed by broad range of cells and involved in uptake of many self- or non-self-particles, it contributes to a varied list of physiological and pathologic processes such as apoptotic cell clearance, angiogenesis, atherosclerosis, Alzheimer's disease and infectious diseases." (PMID 22287954, 2012). "CD36 might become a novel target for the prevention and treatment of atherosclerosis." (PMID 21486455, 2011). "Therefore, an increased level of soluble forms of CD36, which has been reported to be increased in type II diabetic patients, could accelerate atherosclerosis by increasing the pro-inflammatory response to diacylglycerol ligands." (PMID 19847289, 2009). "Given the established association between increased CD36 expression on platelets and the progression of the atherosclerotic process, one might speculate that treatment with PCSK9i does not appear to beneficially affect the process of atherosclerosis." (PMID 40002707, 2025).
atherosclerosis (continued). "Path analysis demonstrates the interrelationships of Citrullus lanatus (CL), PCSK9, LOX-1, CD36, ABCA1, and foam cell (FC) formation in atherosclerosis." (PMID 40699832, 2025). "This study aimed to explore the effects of red watermelon extract on the expression of PCSK9, LOX-1, ROS, TNFα, CD36, and ABCA1 in a Wistar rat model of atherosclerosis." (PMID 40699832, 2025). "To investigate the critical role of lipid metabolism in atherosclerosis progression and the potential alteration of CD36 in atherosclerosis lesions, we employed a high-fat diet (HFD)-induced ApoE−/− mouse model of atherosclerosis." (PMID 40284439, 2025). "This study was conducted to explore how red watermelon (Citrullus lanatus) consumption modulates the lipid profile, and the expression of PCSK9, LOX-1, CD36, ROS, TNFα, and ABCA1 so that it can inhibit the development of atherosclerosis." (PMID 40699832, 2025). "This increase was attenuated in Apoe/Cd36 double-null mice under both chow and HFD conditions, consistent with prior findings showing protection from chronic inflammation and atherosclerosis in these mice." (PMID 40250804, 2025). "Red watermelon has potential in atherosclerosis prevention by modulating the expression of PCSK9, LOX-1, CD36, ROS, TNFα, and ABCA1." (PMID 40699832, 2025). "Due to their ability to bind modified lipoproteins, specifically oxidized low-density lipoprotein (oxLDL), numerous scavenger receptors (CD36, LOX-1, MARCO, SR-B1, SR-PSOX, and SR-A1) have been shown to contribute to atherosclerosis progression." (PMID 40512027, 2025). "We found CD36+ endothelial cells, VEGFA+ macrophages and adventitial fibroblasts play critical roles in the occurrence and progression of atherosclerosis." (PMID 40594772, 2025). "The scavenging receptor CD36 is one of the genes commonly expressed in LAM in obesity, atherosclerosis and cancer." (PMID 39911578, 2024). "Curcumin reduces the expression of CD36, a cell surface receptor crucial for recognizing and internalizing oxidized LDL, thereby inhibiting the development of atherosclerosis." (PMID 39457594, 2024). "In sum, these results suggested that oxLDL enhanced the interaction between CD36 and TLR4 in ECs and further triggered NF-κB signal transduction, which was related to the effect of Ash2l in promoting atherosclerosis." (PMID 38280036, 2024). "Atorvastatin inhibits atherosclerosis and NSCLC by down-regulating the expression of MMP9, MMP12, FABP4, and CD36." (PMID 37978381, 2023). "CD36 participates in NAFLD, atherosclerosis, chronic kidney disease, diabetes mellitus, immunity, and cancer." (PMID 40625574, 2023). "This review focuses on the link between IR, T2DM, atherosclerosis, CAD, and the potential genetic markers CHI3L1, CD36, LEPR, RETN, IL-18, RBP-4, and RARRES2 genes." (PMID 36984867, 2023). "Related to this, CD36 is a fatty acid translocase that enhances cellular FFA uptake and corresponding development and progression of lipid disorders, atherosclerosis, and metabolic syndrome." (PMID 37610001, 2023). "In atherosclerosis, ox-LDL can be taken up by macrophages through CD36 and transformed into foam cells, secreting inflammatory cytokines and chemokines." (PMID 36903257, 2023). "The macrophage scavenger receptor, CD36, has been shown to accelerate the uptake of oxidized low-density lipoprotein (ox-LDL), thereby promoting foam cell formation within the atherosclerosis." (PMID 37047475, 2023). "Monocytes and macrophages, whose surfaces carry, among other things, scavenger receptors such as CD36 and others responsible for binding oxidized LDL (oxLDL) particles and their accumulation by macrophages, influence atherosclerosis pathomechanism." (PMID 37239003, 2023). "Previous studies have documented that CD36 and GSH play crucial roles in processes such as inflammation and oxidative stress responses of arterial walls in cardiovascular diseases such as atherosclerosis." (PMID 38196515, 2023).